BCL2 (BCL2 apoptosis regulator)
Diseases named in the same sentence as BCL2 in open-access papers (continued):
Sharing a sentence is not in itself a finding about the gene and the disease.
endometriosis (continued). "As an antiapoptotic factor with an elevated expression in ECSC, Bcl-2 may be a target for miR-503, which causes endometriosis cells to die by downregulating Bcl-2 expression." (PMID 36143357, 2022). "Possibly, polymorphic variants of Bax -248G>A and Bcl-2 -938C>A promoter regions might result in the altercations in transcription factor binding to the promoter, leading to the change of gene expressions, which might be associated with endometriosis." (PMID 39205918, 2024). "pAKT (phosphorylated AKT), γH2AX, BIM, and BAX were overexpressed in EAOCs and contiguous endometriosis as compared to benign endometriosis (p < 0.05), while pATM, pCHK2, and Bcl2 were downregulated." (PMID 40364006, 2025). "Combined oral contraceptives administered to patients with endometriosis leads to a significant decrease in cell proliferation and stimulation of apoptosis in the eutopic endometrium, and a reduction in Bcl-2 levels is observed." (PMID 40243611, 2025). "The expression of the pro-survival member BCL-2 was decreased in the ovaries of rats with endometriosis (p < 0.05 vs. Sham)." (PMID 40002761, 2025). "The correlation between epithelial Bcl-2 expression and the intensity of dyspareunia highlights a potential molecular link to the severity of symptoms in endometriosis." (PMID 40243611, 2025). "In contrast, the index was lower (<8%) in mild endometriosis cases, such as superficial peritoneal lesions, indicating BCL-2’s potential role in lesion survival and severity." (PMID 40649777, 2025). "While women with minimal/mild endometriosis and moderate/severe endometriosis were considered distinctly, there were some differences for Bax -248G>A rs4645878 and, Bcl-2 -938C>A rs2279115 SNPs." (PMID 39205918, 2024). "Considering the increased cell adhesion activity in endometriosis, the role of BCL2 in the cell adhesion mechanism in endometriosis should be clarified." (PMID 37626707, 2023). "Several papers reported that the increase in the anti-apoptotic protein Bcl-2 hasten the progression of endometriosis." (PMID 36499679, 2022). "Our data based on the Bax/Bcl-2 ratio confirm the decreased apoptosis in endometriosis stromal cells." (PMID 35059465, 2022). "We evaluated, using immunohistochemical analysis of the expression of the cell proliferation marker (Ki67) and by Western blot analysis, the anti-apoptotic protein Bcl-2 and the pro-apoptotic protein Bax expressions in the endometriosis lesions." (PMID 34064310, 2021). "FC can also decrease the expression of the anti-apoptosis protein Bcl-2 and increase the expression of Bax, which suggests that FC-induced apoptosis is able to inhibit endometriosis progression." (PMID 33266505, 2020). "Endometriosis is an inflammatory disease caused by increased TNF-α and IL-1β, which reduce the protein expression of Bax and increase Bcl-2 to inhibit the apoptosis of endometriotic lesions." (PMID 33266505, 2020). "The anti-apoptotic BCL-2 gene, upregulated in the eutopic endometrium of women with endometriosis, enhances cell survival and thus plays a major role in the pathogenesis of endometriosis." (PMID 29937493, 2018). "Increased proliferation and decreased apoptosis rates in the eutopic endometrium correlate with the expression profile of the BCL-2 gene in endometriosis patients." (PMID 29937493, 2018). "As a regulator of apoptosis, Bcl-2 was shown to be significantly increased in the eutopic endometrium of women with endometriosis, leading to the inhibition of apoptosis in the endometrium." (PMID 26377086, 2015). "Apoptotic resistance is mediated by BCL2, leading to enhanced survival of stressed endometrial cells in endometriosis." (PMID 24927773, 2014). "First, danazol, an androgen analog used for treatment of endometriosis, directly binds to the AR of endometriotic tissue and decreases the expression of Bcl-2 (a suppressor for apoptosis), resulting in the cell death of endometriotic tissue." (PMID 23139742, 2012).
endometriosis (continued). "Studies have shown that increased expression of the Bcl-2 protein is present in the proliferative eutopic endometrium of patients with endometriosis." (PMID 23554610, 2010). "While numerous studies have documented alterations in the expression of ER, PR, and apoptotic regulators like BCL-2 across different endometriosis tissues and menstrual phases, the findings are often inconsistent, reflecting variability in study designs, patient populations, and lesion types." (PMID 40649777, 2025). "This distribution may indicate an increased level of cell proliferation as the stage of endometriosis advances, and implicitly, the potential value of Bcl-2 as a biomarker of aggressiveness." (PMID 40243611, 2025). "In endometriosis, BCL2 is influenced by mir-148a and CCL19/CCR7 via the PI3K/Akt signaling pathway." (PMID 37626707, 2023). "Of these genes, BCL2 is a well-characterized proliferation-related gene involved in endometriosis." (PMID 37626707, 2023). "Evaluation of apoptosis-related genes showed that E-MenSCs significantly decreased mRNA expression of BAX (proapoptotic gene) (0.052 fold, P = 0.05) and significantly increase mRNA expression of BCL-2 (antiapoptotic gene) (1.60 fold, P = 0.01) in endometriosis cells, as compared with NE-MenSCs." (PMID 35059465, 2022). "In brief, JFS might be applied for various diseases through multiple targets and pathways, especially endometriosis by Bcl-2 pathway." (PMID 31781263, 2019). "Inappropriate signal transduction was related to the dysregulated expression of proteins involved in the modulation of apoptosis, such as the increased expression of Bcl-2, that along with bax represent the key proteins of apoptosis regulation in endometriosis." (PMID 31717614, 2019). "BCL2 is targeted by miR-15b/16 and the reduced expression of these miRNAs may contribute to increased activity of this anti-apoptotic protein in endometriosis." (PMID 24927773, 2014). "The PPI network analysis reveals hub genes, including BCL2, CCNA2, CDK7, EGF, GAS6, MAP3K7, and TAB2, which emerge as pivotal players in endometriosis progression." (PMID 39108650, 2024). "In that regard, here we showed that rats subjected to endometriosis presented a reduced number of TUNEL-positive cells and reduced expression of proapoptotic proteins Bax and caspase 3 as well as increased Bcl-2." (PMID 36982152, 2023). "In general, with regard to above findings, increased gene expression of Bcl-2 and Bcl-xL as anti-apoptotic proteins in EESCs and decreased gene expression of caspase-3 in EuESCs, may hamper apoptosis and lead to abnormal cell growth in ectopic locations and the development of endometriosis." (PMID 31906916, 2020). "In the progression of endometriosis, it has been shown that CD147 enhances cell viability of human endometrial cells by up-regulating Bcl-2 through extracellular signal-regulated kinases signaling." (PMID 27902973, 2017). "The expression of Bcl-2 and Ki-67 was not correlated with a personal history of endometriosis, with previous surgical interventions for endometriosis or painful symptoms (dysmenorrhea, dyspareunia, chronic pelvic pain, or gastrointestinal symptoms)." (PMID 40243611, 2025). "Epithelial Bcl-2, stromal Bcl-2, epithelial Ki-67 and stromal Ki-67 were not statistically significantly correlated with a personal history of endometriosis or with a history of surgery for endometriosis." (PMID 40243611, 2025). "In addition, rutin, one of the flavonoids of Codium fragile, inhibited apoptosis by regulating the expression of BCl-2/BAX ratio, Caspase-9, and cleaved poly ADP-ribose polymerase (PARP) in endometriosis development in a rat model." (PMID 37760047, 2023). "In addition to all of that, even the expression of BCL-2 and BAX is changed in peritoneal macrophages during the endometriosis and so the process of apoptosis is delayed and resistance of disease to immune system is increased." (PMID 32082539, 2020).
endometriosis (continued). "We aimed to examine resveratrol effects on gene expression of Bcl-2, Bax and Bcl-2/Bax ratio in endometrial stromal cells derived from women with and without endometriosis." (PMID 33083332, 2020). "Overexpression of EPHA3 inhibited the activation of the mTOR signaling pathway, down-regulated bcl-2 expression, up-regulated the expression of Atg3, LC3-II/LC3-I, Beclin1, bax and fas, and also promoted the autophagy and apoptosis of macrophages in endometriosis mice." (PMID 31262977, 2019). "Furthermore, we previously demonstrated that Bcl-2 and VEGF-A expression was upregulated in ECSCs, and this upregulation was responsible for the anti-apoptotic and angiogenic features of endometriosis." (PMID 28720098, 2017). "Our results demonstrate that in the formed lesions, sIL-1 RII decreased the expression of Bcl-2 and VEGF compared with both control and IL-1 groups, and may contribute to decreasing the size of already formed lesions in the endometriosis nude mouse model." (PMID 23554610, 2010). "sIL-1 RII may suppresse hyperplasia of ectopic endometriosis, perhaps by reducing the expression of certain cytokines, such as VEGF, IL-8, and Bcl-2, which could provide a new clinical strategy for the treatment of endometriosis." (PMID 23554610, 2010). "Interestingly, endometriosis-like lesions developed in MIF-KO mice showed a significant down-regulation of BCL2, which promotes cell survival, but no noticeable change in the expression of the apoptotic BCL2-family member BAX, which binds to BCL2 and counteracts its apoptosis-preventing effects." (PMID 25329068, 2014). "reuteri alone did not alter endometriosis-related proteins, but in the presence of E2G, it reduced BAX/Bcl-2 ratios and increased p-NF-κB, suggesting anti-apoptotic and pro-inflammatory shifts." (PMID 42089668, 2026). "Therefore, through increased expression of bax and fas and decreased expression of bcl-2 in this study, we hypothesized that EPHA3 promoted the apoptosis of macrophages, with evidence supporting the role of EPHA3 as a potential therapeutic target for the treatment of endometriosis." (PMID 31262977, 2019).
Parkinson disease (40 papers, 2013 to 2025). A progressive degenerative disorder of the central nervous system characterized by loss of dopamine producing neurons in the substantia nigra and the presence of Lewy bodies in the substantia nigra and locus coeruleus. "The apoptotic pathway is a critical pathway upregulated in Parkinson’s disease, where damage-associated molecular patterns (DAMPs) increase apoptosis by limiting anti-apoptotic protein Bcl-2 and increasing pro-apoptotic proteins Bcl-xl in the MPTP-induced PD animal model." (PMID 39844853, 2024). "A direct role for the Bcl-2 proteins in mitochondrial dynamics has been shown in the activation of cell death in Drosophila melanogaster during mid-oogenesis and in the Pink1 loss-of-function Parkinson disease model." (PMID 27192974, 2016). "For Parkinson’s disease, resveratrol activated the anti-apoptotic factor Bcl-2 and inhibited caspase-3 activity in SH-SY5Y neuroblastoma cells." (PMID 41572967, 2025). "β-Asarone inhibits the PERK/CHOP/Bcl-2/Beclin-1 pathway to alleviate ER stress and excessive autophagy in Parkinson’s disease rat models, reducing PERK phosphorylation, CHOP expression, and Beclin-1 release, while increasing Bcl-2 levels to inhibit autophagy." (PMID 40337511, 2025). "Ginkgetin and bilobalide decrease levels of intracellular ROS, maintain mitochondrial membrane potential, and inhibit cell apoptosis via caspase-3 and Bcl2/Bax pathways to exert antioxidant effects in the mouse model of Parkinson’s disease." (PMID 39106233, 2024). "The genetic markers of Parkinson’s disease BCL2, TBP,and TAF1 exert greater regulatory influence on acylcarnitinemetabolism enzymes, while PARP1 equally affects enzymesinvolved in both amino acid and acylcarnitine metabolism." (PMID 39944797, 2024). "BBF was reported to inhibit the expression of Cx43 and reduce the ratio of Bax/Bcl-2 to produce anti-Parkinson’s neuroprotective effects." (PMID 36015166, 2022). "Asiaticoside was found to be beneficial in MPTP-induced Parkinsonism due to its neuroprotective potential that includes its antioxidant activity, by regulating the dopamine metabolic balance and enhancing the Bcl-2/Bax ratio." (PMID 36296397, 2022). "A study investigated that inhibition of ITGA7 down-regulated the expression of BCL2 and increased the BAX/BCL2 ratio, causing apoptosis of SH-SY5Y cells in Parkinson’s disease mouse models." (PMID 36204112, 2022). "Piperlongumine inhibits apoptosis by phosphorylating BCL2 at S70 in a mouse model of rotenone-induced Parkinson’s disease." (PMID 35183115, 2022). "Madecassoside decreases the depletion of dopamine and its metabolites, and the malondialdehyde (MDA) level significantly enhances the striatal BDNF level and modulates the ratio of Bcl-2/Bax in MPTP-induced PD in Wistar rats for Parkinson’s disease research." (PMID 34054540, 2021). "Resveratrol may have an impact on BCL-2 activity towards enhancing mitochondrial health, which is crucial for protecting neurons in Parkinson’s disease." (PMID 40404673, 2025). "Similar mechanism of action had been observed in an earlier study using MPTP‐treated mice where asiaticoside administration prevented oxidative damage to the neurons and protected against Parkinson's toxicity specifically by blocking Bax‐mediated neuronal death and promoting Bcl‐2 expression." (PMID 36756687, 2023). "Madecassosides have been reported to exhibit neuroprotective activity in MPTP-induced Parkinsonism models and could retrieve the DA (dopamine) depletion and enhance the Bcl-2/Bax ratio and BDNF protein expression." (PMID 36296397, 2022). "Exposure to mild hyperbaric oxygen activates oxidative metabolism in dopaminergic neurons in the substantia nigra, which inhibits the reduction in dopaminergic neurons and oxidative stress and protects against Bax/Bcl-2-mediated apoptosis, thereby resulting in an attenuation of Parkinson’s disease." (PMID 36421475, 2022).
Parkinson disease (continued). "Moreover, Withania somnifera has shown a significant improvement in movement disorders and dopaminergic neuroprotection, paraquat-induced Parkinsonism, and downregulation of iNOS and Bax and induction of Bcl-2 protein expression in Maneb." (PMID 36589679, 2022). "Moreover, dietary supplementation of AST esters significantly suppressed the protein expression of Bax, Cyt-C, and Caspase 3, as well as upregulated Bcl-2 levels in the brain of mice with Parkinson’s disease." (PMID 34564161, 2021). "Additionally, ferulic acid can significantly reduce seizure intensity, myoclonic spasms, and cognitive decline in epileptic mice, and can reduce the Bax/Bcl2 ratio in dopaminergic neurons in the striatum in mice with Parkinson’s disease (PD)." (PMID 32760268, 2020). "In this regard, BAX, another member of the BCL2 gene family, immunolocalizes in lysosomes in a variety of cell lines exposed to pro‐apoptotic stimuli and in experimental models of Parkinson's disease, where it has been shown to induce lysosomal membrane permeabilization and lysosomal dysfunction." (PMID 35263007, 2022). "β-Asarone modulates the JNK/Bcl-2/Beclin-1 pathway, reducing JNK and p-JNK expression while increasing Bcl-2 and Beclin-1 levels in the striatum of 6-OHDA-induced Parkinson’s model rats, attenuating excessive autophagy." (PMID 40337511, 2025). "Madecassoside also exhibits similar properties, as seen in another study where the compound prevented early signs of Parkinsonism in MPTP‐treated rats by reversing the depletion of dopamine, upregulating antioxidant activity and increasing the Bcl‐2/Bax ratio." (PMID 36756687, 2023). "In the study of Parkinson's disease, Gyps are able to decrease the expression level of LDH, Bax, cytochrome c, caspase-3-9, and PPAR and increase the expression level of Bcl-2." (PMID 36157877, 2022). "Our previous studies showed how in an experimental model of Parkinson’s disease, LGF potentiates cell survival through the regulation of Bcl2 and Bax protein expression." (PMID 33276671, 2020). "Current studies have demonstrated oligo-porphyran offers a neuroprotective treatment for Parkinson’s disease via PI3K/Akt/GSK-3β pathway, with changes in the Bax/Bcl-2 ratio." (PMID 31168297, 2019). "The licorice (root of Glycyrrhiza glabra) inhibited dopaminergic apoptotic cell death as evidenced in the increase in Bcl2 levels and in the decrease in Bax levels, caspase-3 activity, cytochrome c release, and JNK and MAP activities in a model of 6-OHDA-induced Parkinson's disease." (PMID 26064418, 2015). "Furthermore, the high Bcl‐2/Bax ratio accounts for reduced ROS generation and higher GSH‐stabilized antioxidant activity via the action of Bcl‐2, thus contributing to enhanced resistance against MPTP‐induced Parkinsonism." (PMID 36756687, 2023).